AFP (alpha fetoprotein)
Diseases named in the same sentence as AFP in open-access papers (continued):
Sharing a sentence is not in itself a finding about the gene and the disease.
seminoma (continued). "One patient with a seminoma but with slight AFP elevation pre- and post-orchiectomy (interpreted clinically as a constitutional elevation of this marker) was decided to be put on surveillance; remarkably, the hsa-miR-371a-3p was negative in the post-orchiectomy follow-up samples of this patient." (PMID 35756620, 2022). "Also, of interest, a seminoma patient showed an elevation of AFP pre-operatively, which he maintained post-orchiectomy and during follow-up." (PMID 35756620, 2022). "Additionally, FOXA2 was sensitive enough to detect few YST cells in bulk tumour masses, like classical seminomas with elevated serum AFP levels, which has an important implication for clinical use; i." (PMID 33448076, 2021). "Moreover, a relevant and sustained elevation of AFP in a tumor determined to be pure seminoma histologically dictates that, clinically, the patient should be considered a non-seminoma." (PMID 33800799, 2021). "We also analysed three seminoma patients showing increased levels of serum AFP." (PMID 33448076, 2021). "AFP and hCGβ had sensitivities of 52% and 51% in the non-seminomas." (PMID 34341387, 2021). "A search for novel biomarkers for seminomas is particularly warranted because the existing clinical markers such as human chorionic gonadotropin (hCG) and/or α-fetoprotein (AFP) are used primarily as reliable biomarkers and proxy for the presence of non-seminomas." (PMID 32466562, 2020). "Moreover, in presence of testicular or mediastinal mass an elevated alpha–fetoprotein strongly suggests a non–seminoma germ–cell tumor especially in young patients." (PMID 28407756, 2017). "However, in the literature, few cases have been described of patients with histologically pure seminoma presenting with elevated serum AFP levels." (PMID 27150447, 2016). "Intermediate risk non-seminoma is disease without evidence of nonpulmonary visceral metastases and post-orchiectomy markers any of: AFP=1,000–10,000 ng/mL, HCG=5,000-50,000 iu/L, and LDH=1.5–10 × upper limit of normal." (PMID 20535291, 2010). "Poor risk non-seminoma is disease with a mediastinal primary tumor or nonpulmonary visceral metastases or post-orchiectomy markers any of: AFP > 10,000 ng/mL, HCG > 50,000 iu/L, and LDH > 10 × upper limit of normal." (PMID 20535291, 2010). "Intermediate risk seminoma is comprised of disease at any primary site with nonpulmonary visceral metastases and normal AFP, any HCG, and any LDH." (PMID 20535291, 2010). "Good risk seminoma is disease at any primary site without nonpulmonary visceral metastases and normal AFP, any HCG, and any LDH." (PMID 20535291, 2010). "Notably, focal gains spanning AFP (4q13.2) were also restricted to a subset of seminomas (8/57)." (PMID 39461959, 2024). "A pure seminoma may also produce AFP, but should then be managed as a non-seminoma cancer." (PMID 22559879, 2012). "Comparatively, serum tumor markers AFP, LDH, and β-hCG had sensitivities of less than 50% in seminomas." (PMID 38611057, 2024). "More specifically, these investigators reported that among all GCT patients (seminoma and NSGCT), the sensitivity of AFP was 18%, β-hCG 35%, LDH 28%, and about 50% for all three STMs combined among GCT." (PMID 39685906, 2024). "HCG, age at surgery, NSGCT histology, LDH, AFP, LVI and percentage of seminoma histology were crucial factors for discrimination of the three hormonal subsets." (PMID 37669975, 2023). "Both in the ‘neutral’ and ‘pituitary’ subset, AFP/HCG + tumors were more frequently classified as NSGCT as compared with AFP/HCG- cancers, which were predominantly seminoma." (PMID 37669975, 2023). "Both in the ‘neutral’ and ‘pituitary’ subset, AFP/HCG + tumors were more frequently classified as NSGCT, compared to AFP/HCG-negative GCTs, which were predominantly seminoma." (PMID 37669975, 2023). "The AFP and HCG values of most seminomas and spermatocytic tumors are normal, which is consistent with the literature reports." (PMID 36550425, 2022).
seminoma (continued). "Laboratory examinations: AFP and HCG were elevated in two mixed germ cell tumors; HCG was elevated in one seminoma; AFP was elevated in one embryonal carcinoma; and follicle-stimulating hormone and luteinizing hormone were elevated in one bilateral lymphoma." (PMID 36550425, 2022). "Among the non-seminomas CS1, 50% expressed AFP and 46% expressed hCGβ above the reference thresholds." (PMID 34341387, 2021). "Compared with the seminoma / EC cell lines, the aYST cell line GCT72 showed high expression of the proposed YST factors (except AFP and FGB), respectively." (PMID 33448076, 2021). "Tumor markers (βHCG and/or AFP) are elevated at relapse in about 2/3 of NSGCT and approximately 1/3 of seminomas." (PMID 32102532, 2020). "For seminoma, this included LZTS1; for EC, DNMT3B, GAL and GPC4; for CHC CGA; and for YSTs AFP, APOA2, BMP2, VTN and OTX2." (PMID 25303610, 2015). "It is commonly expressed by syncytiotrophoblasts found in CC and approximately 15% of seminomas, while AFP can be normal in 50%-70% of non-seminomatous GCTs (NSGCT)." (PMID 40656238, 2025). "In the current study, AFP and β-HCG levels were elevated to 87.2 ± 28.2 ng/mL and 81.4 ± 31 IU/L, respectively, in the non-seminoma group, whereas both markers remained within the normal range in seminomas." (PMID 41527642, 2025). "In most subjects with moderate elevations of AFP at BL, AFP remained stable during follow-up, and none relapsed within the study period following treatment for seminoma." (PMID 39934683, 2025). "Consistent with previous studies, our results demonstrated significantly higher AFP and β-HCG levels in non-seminomatous tumors compared to seminomas, confirming their diagnostic specificity." (PMID 41527642, 2025). "AFP can be only expressed by NSGCT, while HCG can be produced by seminomas and NSGCTs, as well." (PMID 40011822, 2025). "The normal HCG level helped differentiate the tumor type, as seminomas typically elevate HCG but not AFP." (PMID 39171067, 2024). "Significant elevation of AFP in patients with seminomas should raise concerns about a non-seminoma component." (PMID 38674232, 2024). "By contrast, serum bHCG is elevated in less than 20% of testicular seminomas, and AFP is not elevated in pure seminomas where an increase of AFP indicates a non-seminoma component." (PMID 38958901, 2024). "Measurement of the serum concentrations of hCG and lactate dehydrogenase before and after orchiectomy is recommended for patients with pure seminoma and non-seminomatous TGCTs, with the addition of alpha-fetoprotein (AFP) in the latter case." (PMID 38067334, 2023). "Seminoma is often accompanied by serum β‐human chorionic gonadotropin elevation, and nonspermatoblastoma is often accompanied by alpha‐fetoprotein elevation." (PMID 36924056, 2023). "As GCTs as a whole (SE + NS) were evaluated in the present investigation, AFP scored lower expression rates than bHCG which obviously relates to the non-expression of AFP in pure seminoma." (PMID 36869885, 2023). "High and increasing levels of AFP in a seminoma patient implies ruling out non-seminoma components since these patients should be considered and treated as non-seminoma." (PMID 36831022, 2023). "Although AFP production in pure seminoma is biologically not possible, clinical series repeatedly reported slightly elevated AFP levels in pure seminoma with no changes despite curative treatment." (PMID 36869885, 2023). "The novel marker M371 outperforms all classical markers with expression rates of 82.7% and 93.6% in seminoma and nonseminoma, respectively, and these rates are also significantly higher than the combined rate of AFP and/ or bHCG in nonseminoma (68.7%)." (PMID 36869885, 2023). "Seminoma testicular tumors are not known to secrete AFP, however, unspecified AFP elevations occur in approximately 2% of seminoma patients." (PMID 37485120, 2023).
seminoma (continued). "This trend was found in both seminoma and nonseminoma, with the exceptions of AFP in seminoma (p = 0.9133) and M371 in nonseminoma (p = 0.0745)." (PMID 36358866, 2022). "In all undulating TM cases, of which 50% (3/6 patients) were classified as seminoma, AFP was the elevated TM but did not exceed an absolute value of 20 ng/ml from at least three consecutive post-operative measurements." (PMID 34854948, 2022). "Regarding the classical markers in TGCC, seminomas do per definition not express AFP and hCGβ is expressed at low pathological levels in only ~ 30% of patients." (PMID 34341387, 2021). "Median serum levels (x-fold of ULN) of both, bHCG and AFP, were significantly higher in nonseminoma than in seminoma." (PMID 31275973, 2019). "Comparison of the median marker levels of CS1 patients with the median levels of all metastasized patients (>CS1) revealed significant differences regarding bHCG and LDH but not AFP in both seminoma and nonseminoma." (PMID 31275973, 2019). "A total of 45 cases of false-positive AFP level have been reported in testicular GCTs (TGCTs), 17 of them in non-seminomatous TGCTs and 28 cases in seminoma." (PMID 31836006, 2019). "In our literature review, at least five cases in non-seminomatous GCTs and six cases in seminoma received additional interventions based on a false elevated AFP level." (PMID 31836006, 2019). "In all GCT patients, the frequencies of elevated levels of bHCG, AFP, LDH, and bHCG or AFP were 37.9%, 25.6%, 32.9%, and 47.6%; in pure seminomas 28%, 2.8%, 29.1%, and 30.3%; and in nonseminoma 53.0%, 60.1%, 38.7%, and 73.8%." (PMID 31275973, 2019). "Eight cases of seminomas were clinically considered as non-seminomas based on the positivity of alpha-fetoprotein." (PMID 30390643, 2018). "Serum AFP is elevated in cases such as HCC, seminoma, and pancreatic cancer." (PMID 29390333, 2017). "Since seminoma does not induce AFP production, the guidelines recommend that cases with increased AFP levels be treated as cases of NSGCT." (PMID 27150447, 2016). "Patients with elevated serum AFP levels and a primary pure seminoma are treated as patients with NSGCTs, because some nonseminomatous components are presumed to be present either in the testis or at a metastatic site." (PMID 27150447, 2016). "Among them, alpha-fetoprotein (AFP), beta-human chorionic gonadotropin (β-HCG), and lactate dehydrogenase (LDH) are routinely utilized for differential diagnosis between seminoma and non-seminoma, as well as for evaluating treatment response and recurrence risk." (PMID 41527642, 2025). "Any elevation of AFP rules out pure seminoma and categorizes the tumor as nonseminoma." (PMID 40443838, 2025). "Pure seminomas do not secrete AFP, and this can be used to distinguish them from mixed GCTs." (PMID 40182369, 2025). "The present results are in accordance the international consensus that mildly elevated AFP levels with no clinical significance may occur in isolated cases with seminoma." (PMID 36869885, 2023). "Although seminomatous GCT by definition does not produce AFP, this marker is assessed during follow-up as a few patients initially diagnosed with seminoma may experience recurrence with an AFP-producing nonseminomatous GCT." (PMID 36106144, 2022). "Seminomas may exist in a pure form, but any elevation of AFP indicates the presence of an element of a non-seminomatous tumor." (PMID 33005196, 2020). "Pure tumours (TC choriocarcinoma and seminoma) do not have the potential to produce AFP." (PMID 31652641, 2019). "Therefore, pure seminomas with elevated serum AFP levels have a relatively lower sensitivity to chemotherapy than pure seminomas without elevated serum AFP levels or NSGCTs." (PMID 27150447, 2016). "Seminoma tumors do not increase AFP levels, and occasionally increase hCG." (PMID 19709439, 2009). "However, some EGCTs, such as seminomas, do not exhibit an increase in AFP." (PMID 37138865, 2023).
seminoma (continued). "Biochemically, pure seminomas do not produce AFP but may produce a small amount of β-HCG." (PMID 30563561, 2018). "Serum AFP and β-HCG levels were significantly higher in patients with non-seminoma compared to those with seminoma." (PMID 41527642, 2025). "Specifically, alpha-fetoprotein (AFP) is not elevated in pure seminomas, while human chorionic gonadotropin (hCG) elevation occurs in only a minority of seminoma cases, resulting in false negative outcomes for some patients." (PMID 41283275, 2025). "AFP, β-hCG and LDH had sensitivities of less than 50% in seminoma and slightly higher sensitivities in non-seminoma." (PMID 35204369, 2022). "Only approximately 30% of seminoma patients with advanced disease have serum HCG levels above normal, and unequivocally increased AFP levels are not consistent with pure seminomatous histology." (PMID 33683412, 2021). "This is particularly important in seminomas, which only infrequently (18 to 31%) lead to the elevation of serum tumor markers (HCG, since AFP is by definition negative)." (PMID 33800799, 2021). "The problem with these markers is the lack of sensitivity and specificity: only 20–30% of pure seminomas produce β-hCG and only every second non-seminoma TGCT has elevated LDH, AFP, or β-hCG levels." (PMID 32235691, 2020). "Around 90% of non-seminoma tumors will be positive for AFP or β-HCG and up to 30% of seminomas will be positive for β-HCG." (PMID 31597402, 2019). "At completion of adjuvant therapy elevation rates of bHCG and AFP further decreased to 1-1.3% while LDH elevation rates remained in the range of 10%, in both seminoma and nonseminoma." (PMID 31275973, 2019). "Other markers, including miR-367-3p, AFP, β-HCG, and LDH, were not significantly different in serum samples of seminoma patients in disease recurrence compared to no-evidence-of-disease samples (p > 0.05)." (PMID 30321995, 2018). "Comparing the miRNAs and traditional tumor markers in serum samples from patients with seminomatous and non-seminomatous TGCTs indicated that AFP (p < 0.001) and β-HCG (p = 0.004) were aberrant (increased) in non-seminoma patients." (PMID 30321995, 2018). "Contrary to the classical GCT markers, beta-human chorionic gonadotropin (b-HCG), alpha-fetoprotein (AFP) and lactate dehydrogenase (LDH), miR-371a-3p is expressed both in seminoma and nonseminoma." (PMID 28819887, 2017). "Furthermore, TCam-2-ΔSOX2/FOXA2 derived tumors stained positive for pluripotency and seminoma markers OCT3/4, SOX17, TFAP2C, and PRDM1/BLIMP1, but were negative for the differentiation-markers AFP and EOMES." (PMID 31130628, 2019). "Indeed, rises in levels of AFP and HCG may allow the detection of the tumor and the identification of its type: non-seminomas or pure seminomas; while high LDH levels indicate a widespread disease." (PMID 31450698, 2019).
lymph node metastasis (79 papers, 1995 to 2026). "The univariate analysis indicated that the OS of HAS was associated with tumor location, pTNM stage, lymph-node metastasis, surgical resection, and serum AFP > 300 ng/ml." (PMID 37161409, 2023). "A high level of serum AFP (>20 ng/ml) was associated with a high incidence of lymph node metastasis, venous and nerve invasion, liver metastasis, and a poor prognosis." (PMID 35847953, 2022). "In conclusion, a high level of serum AFP in GC was associated with a high incidence of lymph node metastasis, venous invasion, nerve invasion, liver metastasis, and a poor prognosis." (PMID 35847953, 2022). "Further, high alpha-fetoprotein level (> 10 ng/mL), large tumor size (> 5 cm), and presence of microvascular invasion have been reported as risk factors for lymph node metastasis in HCC." (PMID 34918186, 2021). "After grouping, YAP/TAZ-positive HCCs were significantly associated with higher serum AFP levels (p = 0.024), more frequent microvascular invasion (p = 0.011), higher T stage (p = 0.017) and lymph node metastasis (p = 0.003)." (PMID 34257565, 2021). "Univariate analysis results indicated that tumor location, pTNM stage, lymph-node metastasis, surgical resection, and serum AFP > 300 ng/ml were associated with the OS of HAS(P < 0.05).However,the prognostic risk factors for PFS only included pTNM stage and surgical resection." (PMID 37161409, 2023). "Lymph node metastasis, nerve invasion, and preoperative AFP might be the risk factors of tumor recurrence of SMGC, but need further validation." (PMID 33478518, 2021). "Lymph node metastasis, nerve invasion, and preoperative AFP might be associated with recurrence of SMGC, needing further validation." (PMID 33478518, 2021). "Univariate logistic regression identified seven factors significantly associated with lymph node metastasis (LNM; p < 0.05): age, sex, race, sequence number, tumor size, T stage and AFP status." (PMID 40718824, 2025). "The Higher sADC group had a lower risk of short OS, with exceptions in the subgroups of female, PD-L1 usage, with PVTT, with lymph node metastasis, Child–Pugh B, smoking, and AFP ≥ 400 ng/mL." (PMID 41137952, 2025). "Patients with AFP-positive status frequently present with larger tumors, higher rates of lymph node metastasis, and more frequent liver metastasis, all of which are commonly linked to a poorer prognosis." (PMID 40485723, 2025). "A central finding of our study is the link between AFP positivity and advanced clinical as well as pathological features, including larger tumor size, deeper invasion (T-stage), more frequent lymph node metastasis (N-stage), and presence of distant metastasis." (PMID 40485723, 2025). "AFP increased after surgery in 18.6% of the patients, lymph-node metastasis occurred in 84.6%, and liver metastases were present in 39.1% before surgery." (PMID 37161409, 2023). "In our nomogram, we combined seven variables (PLT, CEA, AFP, tumor location, tumor differentiation, lymph node metastasis, and chemotherapy) recognized from multivariate analysis with the TNM stage to optimize clinical practice." (PMID 37308861, 2023). "PLT, CEA, AFP, tumor location, differentiation, lymph node metastasis, chemotherapy, and TNM stage were determined to be independent risk factors for CCA patients by univariate and multivariate Cox proportional hazard regression analysis." (PMID 37308861, 2023). "Univariable analysis revealed that treatment type, ECOG performance status, Child–Pugh class, pretreatment AFP level, tumor size, disease extent, lymph node metastasis, and PVTT type were prognostic factors for OS both before and after PSM." (PMID 37370774, 2023). "Regarding PFS, treatment type, ECOG performance status, Child–Pugh class, pretreatment AFP level, tumor size, disease extent, and lymph node metastasis were prognostic factors in the univariable analysis." (PMID 37370774, 2023).